MIR320C1 (microRNA 320c-1)
Synonyms: hsa-mir-320c-1; MIR320C-1; MIRN320C1; mir-320c-1
Gene: MicroRNA gene on chromosome 18 (21,683,510 to 21,683,597, forward strand). Ensembl gene ENSG00000221493.
Gene Ontology:
Biological process: cellular response to glucose stimulus; long-term synaptic potentiation; miRNA-mediated post-transcriptional gene silencing; negative regulation of gene expression; positive regulation of stem cell proliferation
Cellular component: RISC complex
Diseases named in the same sentence as MIR320C1 in open-access papers:
MIR320C1 is named in the same sentence as 1 disease in open-access papers, as found by Europe PMC text mining. Sharing a sentence is not in itself a finding about the gene and the disease.
MIR320C1 shares sentences with these, for which no sentence is quoted: lung disease (1 paper).